CXCR2 (C-X-C motif chemokine receptor 2)
Diseases named in the same sentence as CXCR2 in open-access papers (continued):
Sharing a sentence is not in itself a finding about the gene and the disease.
tumor (continued). "CXCL1 released from CRC cells induces CXCR2+ endothelial cell migration, causing increased tumor microvessel formation." (PMID 27136535, 2016). "In summary, the current study highlights a novel role of CXCR2 signaling in mediating KRAS(G12D) mutation-induced autocrine growth transformation of tumor cells by directly modulating the levels of KRAS protein and its downstream signaling." (PMID 26771140, 2016). "Studies have also shown that CXCL8, CXCR1, and CXCR2 have been associated with tumor progression in melanoma by means of affecting the growth of the tumor cells, angiogenesis, and metastasis." (PMID 27379162, 2016). "CXCR2 positivity combined with postoperative complications was an independent risk factor for subsequent tumor recurrence, showing the highest hazard ratio." (PMID 26231560, 2015). "The CXCR2(+)/complication(+) status was an independent risk factor for subsequent tumor recurrence, showing the highest hazard ratio compared with the other preoperative variables and each pathologic feature." (PMID 26231560, 2015). "Among CXCR2-mediated cytokines, we found some CXCLs increased more than tumor increase and some were associated with tumor size." (PMID 26414070, 2015). "High CXCR2 expression was associated with poor tumor differentiation (p = 0.021), increased tumor depth (p < 0.001), lymph node metastasis (p < 0.001), advanced TNM stage (p < 0.001) and short OS (p = 0.001)." (PMID 26497045, 2015). "Our results indicated that patients with CXCR2-positive tumors who developed postoperative complications were predicted to be at the greatest risk of subsequent tumor recurrence." (PMID 26231560, 2015). "IHC analysis of MLS/RCLS tissues showed that the senescence associated IL8 receptor beta (also known as CXCR2) was expressed in 50–91% of the tumor cells." (PMID 25093008, 2014). "To note, CXCR2 mutation or downregulation cancels its prosenescent action facilitating tumour progression." (PMID 25268744, 2014). "Of note, their cognate G-protein-coupled receptors (GPCR), CXCR1 and CXCR2, are expressed on endothelial cells, tumor cells, and neutrophils/tumor-associated-macrophages, indicative of pleiotropic activities of IL-8." (PMID 23967403, 2013). "Because these molecules are mediators of angiogenesis, the expression of ELR+ and CXCR2 is associated with tumor progression." (PMID 23469080, 2013). "Recent studies have also indicated a role of CXCR2 signaling in promoting the early tumor development of APC-deficient colorectal cancer, wherein polyp formation was significantly depleted by the inhibition of this signaling." (PMID 24276377, 2013). "The evasion of CXCR2-dependent senescence (loss of expression of CXCR2 or p21) is important in restoring the oncogenic properties of hPTTG1 overexpression to promote tumor growth and metastasis." (PMID 22789011, 2012). "There was an association between 5 year survival and tumour islet CXCR2, CXCR3 and CCR1 density (p = 0.02, 0.003 and <0.001, respectively) as well as stromal CXCR3 density (p = 0.003)." (PMID 20429924, 2010). "Additionally, ELISA analysis revealed that the levels of cytokines secreted by tumour-associated M2 macrophages increased and that the levels of M1-associated cytokines concomitantly decreased in response to IL-8/CXCR2 pathway activation." (PMID 41163221, 2025). "However, an increase in tumor-associated CXCR2+ neutrophils compensated for the beneficial effects of CCR2+ macrophage-targeted therapy; therefore, targeting both myeloid cell types appears to be critical to improve response to chemotherapy." (PMID 40917508, 2025). "Also co-depletion of CXCR2+ tumor-associated neutrophils overcomes the compensatory response of neutrophil mobilization by depletion of CCR2+ tumor-associated macrophages." (PMID 40050933, 2025). "In addition, overexpression of CXCR2, a key chemokine receptor in many tumour is linked to poor prognosis." (PMID 40852716, 2025).
tumor (continued). "An increase in CXCL1 expression in the tumor is also observed under the influence of ionizing radiation, mainly due to an increase in the expression of this chemokine and CXCR2 in cancer-associated fibroblasts (CAF), as shown by experiments on esophageal squamous cell carcinoma." (PMID 40427171, 2025). "Myeloperoxidase+ (MPO+) neutrophils and CD11b+Ly6G+ MDSCs infiltration into tumours is reduced in CXCR2 knockout PKF [mice with conditional KrasG12D mutation and knockout of TGF-β receptor type II (Tgfbr2), (LSL-KrasG12D/+; Tgfbr2flox/flox, Ptf1a-Cre] mice compared to control animals." (PMID 38384463, 2024). "We also demonstrated that recruitment of CXCR2+ myeloid cells to SMAD4-deficient CRCs could promote tumor invasion and metastasis, suggesting blockade of the CXCL1/8–CXCR2 axis could be a novel therapeutic approach in CRC." (PMID 38750114, 2024). "In addition, CXCR1 and CXCR2 are also expressed in different cells, such as tumor cells, tumor-associated mesenchymal stromal cells (MSCs), and endothelial cells." (PMID 37765018, 2023). "Furthermore, CXCL8 can recruit CXCR2-expressing tumor-associated macrophages and induce an immunosuppressive M2 phenotype into the tumor microenvironment, as demonstrated e.g. in a murine model for pancreatic cancer." (PMID 36725964, 2023). "Although the absence of ARNT significantly promotes the expression of CXCR2 in neutrophils of BMs and spleen under physiological conditions and pathological tumor-infiltrating neutrophils, can CXCR2 mediate the regulation of ARNT deficiency on neutrophil function?" (PMID 36859266, 2023). "Collectively, MDSCs infiltrated in the lung of 4T1 tumor-bearing mice may be associated with the formation of the pre-metastatic niche and lung metastasis, and CXCR2 and CCR2 might be involved in the recruitment of MDSCs." (PMID 37268941, 2023). "Our finding that loss or inhibition of Cxcr2 activity in melanocytic cells results in changes in markers associated with stemness, neural crest cells, and melanoblasts in association with a reduction of tumor formation and growth is somewhat paradoxical." (PMID 37270599, 2023). "CXCR2 has been associated with increased tumor growth and poor prognosis across multiple cancers." (PMID 37270599, 2023). "Defective expression of chemokine receptors CXCR1 and CXCR2 on the surface of LDNs was linked to a reduced in vitro migratory potential toward tumor-conditioned media in migration assays with LDNs from cancer patients and tumor-bearing mice." (PMID 35328639, 2022). "Similarly, in a lung cancer mouse model CXCR2 inhibition decreased tumor-associated neutrophils, increased anti-tumor T cell activity through enhanced CD8+ T cell activation and increased the therapeutic effect of cisplatin treatment." (PMID 35053602, 2022). "Using established neutrophil-tumor biomimetic co-culture models, we show that the upregulation of CXCR2 increases the recruitment of Tumor-Associated Neutrophils (TANs) towards the BrM, to enable location-favored formation of Neutrophil Extracellular Traps (NETs)." (PMID 35158784, 2022). "Since CXCL1,2,5 and 8 bind to the chemokine receptor CXCR2 which is associated with neutrophil recruitment to tumours, we first confirmed that Cxcr2 is indeed highly expressed in metastasis infiltrating neutrophils and that CXCR2 expression is not affected by gemcitabine treatment." (PMID 35022267, 2022). "Indeed, in a prostate cancer model, inhibition of CXCR2 resulted in decreased tumor growth due to the reeducation of tumor-associated macrophages." (PMID 35158948, 2022). "Our data add nuance to previous findings indicating that depletion of Ly6G+ neutrophilic myeloid-derived suppressor cells unmasks adaptive immunity, or that ablation of CXCR2+ tumor-associated neutrophils augments IFN-γ+CD8+ T-cell infiltration to potentiate FOLFIRINOX responses in PDAC models." (PMID 36107485, 2022).
tumor (continued). "Chen et al30 have proved MC‐LR could increase vascular permeability through IL‐8/CXCR2 signalling in vivo and vitro, which might be associated with the higher CT values in tumour with high content of MC‐LR and deserved for further study." (PMID 33241617, 2021). "CXCR2 expression was upregulated and associated with tumor size in PDAC." (PMID 34439836, 2021). "Previous studies have shown that genetic variants of CXCR2 may affect the development of cancer by regulating tumor angiogenesis and the antitumor immune response pathway." (PMID 34692853, 2021). "Therefore, adipocyte-specific CXCR2 WT and cKO were associated with tumor and ascites burdens, respectively, such that the loss of CXCR2 in adipocytes altered the peritoneal tumor microenvironment of OC." (PMID 34638514, 2021). "In addition, CXCR2 is associated with tumor proliferation and growth in OC resistant cells, showing its role in disease chemoresistant phenotype acquisition and progression." (PMID 34038868, 2021). "The relationship between chosen risk factors (serum CXCL8 and its specific receptor —CXCR2 as well as classical tumor markers and CRP) and GC risk was examined using univariate analysis to assess the risk factors that subsequently were employed in the multivariate model." (PMID 34680333, 2021). "Additionally, the CXCL8/CXCR2 axis promotes angiogenesis, tumor development and is associated with poor prognosis." (PMID 33390169, 2021). "CXCL1 binds to CXCR2 and has been implicated in tumor growth, angiogenesis, and metastasis." (PMID 33544755, 2021). "CXCL3, another CXCR2-dependent chemokine, is implicated in the recruitment of MDSCs to the tumor." (PMID 35003065, 2021). "Two families of chemokines—CC (CCL-2, 3, 5) and CXC (CXCL-1, 2, 5, 6, 8)—employ CCR-2 with monocytes and CXCR-2+ with neutrophils, at the tumour spot which distinguishes between TAMs and tumour-associated neutrophils (TANs), wielding either pro- or antitumour response." (PMID 34336101, 2021). "In this regard, Cxcr2 plays an important role in governing the pro-inflammatory response in mammary tumors inducing the proportion of Gr1+ tumor-associated granulocytes, F4/80+ tumor-associated macrophages, and CD11b+ Gr1+ myeloid derived suppressor cells (MDSC)." (PMID 33946495, 2021). "In particular, CXCR2 is expressed in neutrophils, and tumor-associated neutrophils (TANs) have been shown to have antitumorigenic (N1) or pro-tumorigenic functions during tumor development." (PMID 34124076, 2021). "Inflammatory CC (CCL2, CCL3, CCL5) and CXC (CXCL1, CXCL2, CXCL5, CXCL6, and CXCL8) chemokines recruit at the tumor site CCR2+ monocytes and CXCR2+ neutrophils that differentiate into tumor associated macrophages (TAMs) and tumor associated neutrophils (TANs), exerting pro- or anti-tumoral role." (PMID 30894861, 2019). "Furthermore, SAP18 expression was found to be up-regulated in hematopoietic stem cells and their progenitor cells (HSPCs) of CXCR2-deficient tumor-bearing mice." (PMID 31395859, 2019). "Intra-tumour neutrophils (MPO) associated with CXCR2 expression(p=0.042)." (PMID 31591445, 2019). "In addition, the loss of CXCR2 expression in stroma cells (neutrophils, macrophages and endothelial cells) in the tumor microenvironment also prevented cancer cell migration." (PMID 31788042, 2019). "To investigate whether the expression of CXCR2 was related to mo-MDSCs accumulation under tumor conditions, we analyzed the number of mo-MDSCs in the blood, bone marrow, and spleen of wild-type (WT) and CXCR2-deficient (CXCR2−/−) mice." (PMID 31395859, 2019). "To explore whether the prolongation of allograft seen in Dex-MDSCs treated mice was due to an enhanced migration of MDSCs, we first assessed the expression of CXCR2, which was implicated in mediating MDSCs recruitment into local inflammatory and tumor sites." (PMID 29497426, 2018). "We found that high- expression of CXCR2 was associated with tumor infiltration and metastasis." (PMID 28415702, 2017).
tumor (continued). "The recruitment of these MDSC subtypes to tumor sites is mediated by chemokines highly expressed by tumor-associated neutrophils, including CXCR2 and CXCR4, and chemokines over-expressed by tumor infiltrating macrophages, including CCR2, CCR5, CXCR4 and CX3CR1." (PMID 26462153, 2015). "In gastric cancer, CXCR2 was found to be associated with tumor progression and invasion." (PMID 26497045, 2015). "Moreover, we generated a predictive nomogram integrating CXCR2 expression, tumor depth, and lymph node metastasis to assess the risk score for 5-year overall survival (OS) of gastric cancer patients." (PMID 26497045, 2015). "Previous studies have also implicated CXCR2 signaling in tumor progression." (PMID 25372289, 2014). "They contribute to the expression of angiogenic CXC chemokines via NF-κB activation in cancer cells, thus enhancing tumor-associated angiogenesis and suggesting for a potential role of 7TM-GPCRs, such as CXCR2, and PTKR in preneoplastic to neoplastic transformation." (PMID 24971349, 2014). "Furthermore, we investigated the association of the CXCR2 (+1208) C/T polymorphism with markers of tumor progression." (PMID 20540789, 2010). "In this paper, we hypothesize that CXCL7 increases the expression of VEGF-C, VEGF-D, and heparanase, and increases cell invasion via CXCR2 signaling, all linked to tumor lymphangiogenesis and metastasis." (PMID 20652010, 2010). "Several studies have implicated CXCR1 and CXCR2 as important players in tumour progression." (PMID 19401689, 2009). "Beyond the tumour, CXCR2-driven biology has been shown to be important in angiogenesis and in infiltrating immune cells, including neutrophils and tumour-associated macrophages (TAMs), suggesting that IL-8 may have a significant pro-angiogenic and tumourigenic role within the TME." (PMID 39199570, 2024). "Previous studies had speculated that extracellular vesicles derived from platelets may facilitate the activation of I-κB and NF-κB pathways through CXCL7/CXCR2 axis in order to promote the tumor-associated biological changes of fibroblast-like synoviocytes in rheumatoid arthritis." (PMID 37393391, 2023). "Moreover, CXCR2-positive MDSCs are attracted to metastatic sites by CXCL1 derived from tumor-associated macrophages (TAM) due to the stimulation of VEGFA released from primary tumor cells." (PMID 35911705, 2022). "Moreover, in tumor models, the inhibition of CXCR2 has been linked to an increased response to immunotherapy, suggesting that the latter may potentially benefit from a combination with CXCR2 inhibitors." (PMID 36295558, 2022). "Thus, CXCR2 activation stimulates the recruitment of tumor-associated neutrophils into BM." (PMID 35884845, 2022). "Furthermore, blocking CXCR2 may have deleterious effects on tumor-associated neutrophils and the effects of such therapies in relation to the relative amount of anti-tumor N1 to pro-tumor N2 TANs in the TME necessitates further study." (PMID 34944914, 2021). "Therefore, in our most recent studies we investigated whether serum CXCL-8 and its specific receptor (CXCR-2) may be used as potential biochemical tumor markers for CRC using the enzyme-linked immunosorbent assays (ELISA) method." (PMID 34071492, 2021). "Therefore, studies on the biological functions of CXCR2 and its association with neoplasia may help improve the prognosis of breast cancer." (PMID 31788042, 2019). "In addition, CXCR2-deficient mice display the characteristics of decreased Gr1+ tumor-associated granulocytes, F4/80+ tumor-associated macrophages, and CD11b+Gr1+ MDSCs, as well as delayed tumor progression." (PMID 31395859, 2019). "Furthermore, we found the expressions of CXCL1 and its receptor CXCR2 were significantly increased 30 min after 8 Gy of radiation in KYSE-150 and KYSE-30, which may cause a constitutively activated CXCL1/CXCR2 signaling in tumor cells." (PMID 28518141, 2017).
tumor (continued). "Therefore, CXCR2 overexpression in tumor microenvironment could be associated with poor prognosis of cancer patients." (PMID 29312644, 2017). "Thus, we hypothesized that the addition of CXCR2 to TNM staging system has the potential to provide more individualized risk stratification based on molecular characteristics of the tumor." (PMID 26497045, 2015). "An increased expression of IL-8 and its receptors CXCR1 and CXCR2 has been demonstrated in cancer cells, infiltrating neutrophils, tumor-associated macrophages and endothelial cells, suggesting a function as a regulatory factor within the tumor microenvironment." (PMID 24281035, 2010). "CXCL5 not only promotes MDSC maintenance via GM‐CSF but also drives their recruitment into the tumor site through the CXCL5/CXCR2 axis, thereby enhancing immunosuppressive activity and tumor progression." (PMID 41532367, 2026). "In agreement, Dox also exhibited better therapeutic efficacy in Cxcr2–/– and Cfb–/– mice with reduced tumor growth and decreased tumoral NET level." (PMID 41480760, 2026). "Given that acetyl-CoA is a key metabolic product of both glycolysis and lipid oxidation, these findings suggest that IL-8/CXCR2 signalling promotes metabolic reprogramming to fuel tumour progression." (PMID 41163221, 2025). "Tumor-associated neutrophils (TANs) have also been shown to be tumor promoting in PDAC and their ablation or inhibition of CXCR2 was found to abrogate metastasis." (PMID 40662361, 2025). "In HCC, despite the inability of CXCR2 knockout to inhibit tumor growth, it was found to promote M1 macrophage polarization in tumors and reduce PD-L1 expression through the mediation of c-Myc down-regulation." (PMID 40959082, 2025). "For example, transducing NK cells with CXCR4 or CXCR2 has enhanced their migration toward chemokine gradients produced by tumours, thereby improving in vivo tumour infiltration and efficacy." (PMID 40624498, 2025). "Pharmacological inhibition of CXCR2 phenocopies the anti-tumor effects of Cebpb ΔIEC deletion, further validating this axis as a therapeutic target." (PMID 40922684, 2025). "High expression of the ligands of Cxcr2, such as Cxcl1, Cxcl2, Cxcl3, and Cxcl5, was observed mainly in tumor cells, fibroblasts, chondrocytes, pericytes and osteoclasts among APM‐naïve cells." (PMID 40433925, 2025). "ELISAs revealed that CXCL15 secretion within the TME increased significantly with tumour growth in both the RM-1 and RM-1/CXCR2 models, peaking at approximately Day 10, whereas the intracellular CXCL15 levels remained unchanged." (PMID 41163221, 2025). "Overall, our findings demonstrate that inhibition of the CXCL15/CXCR2 signalling axis significantly suppresses tumour progression and elicits a robust antitumour immune response in preclinical models." (PMID 41163221, 2025). "Prior research has indicated that the CXCL5/CXCR2 axis has the ability to enhance tumor development and angiogenesis, hence facilitating the infiltration and activation of host cells." (PMID 39670859, 2025). "Lin’s team confirmed through in vivo and in vitro experiments that BMSC can be recruited to the OSCC region and interact with OSCC cells to drive tumor progression via the CXCL8/CXCR2 and TGF-β/Ras/Raf/Erk signaling axes." (PMID 41445742, 2025). "For example, CAR-T cells expressing CXCR2 or CCR5 have demonstrated improved migration toward tumours that produce CXCL1, CXCL8, or CCL5." (PMID 40624498, 2025). "Subsequently, the elevated CXCL2 secretion from tumor cells promotes the recruitment of myeloid‐derived suppressor cells (MDSCs) into the tumor microenvironment (TME) through C‐X‐C chemokine receptor type 2 (CXCR2), thereby facilitating CRC progression." (PMID 40213993, 2025). "When we used our KCC mouse model, with Cxcr2 KO, we saw decreased tumor size and diminished number of infiltrating neutrophils." (PMID 41228334, 2025). "Their tumor-homing potential can be enhanced via genetic engineering of chemokine receptors such as CXCR2 or CCR5." (PMID 40723278, 2025).